HMGB1 (high mobility group box 1)
Diseases named in the same sentence as HMGB1 in open-access papers (continued):
Sharing a sentence is not in itself a finding about the gene and the disease.
leukemia (continued). "Mice that injected with mutated HMGB1 cells or RAGE− cells had better life quality and less leukemia burden." (PMID 34933679, 2021). "Studies demonstrated that HMGB1 was over-expressed in three leukemia cell lines (K562, HL60 and Jurkat) and was correlated to the stage of leukemia." (PMID 34933679, 2021). "For example, HMGB1 inhibits apoptosis in leukemia K562 cells by regulating the protein level of Bcl-2 and the activity of caspase-3 and caspase-9." (PMID 32660524, 2020). "miR-34b was downregulated in patients with t(11q23) AML.The high-mobility group box-1 (HMGB1) functions as an anti-apoptotic protein in leukemia, inhibiting cell apoptosis and inducing cell growth." (PMID 33519805, 2020). "Administration of a polyclonal HMGB1-neutralizing antibody inhibited HMGB1-induced autophagy and increased the sensitivity of leukemia cells to chemotherapy, suggesting that HMGB1 is a potential drug target for therapeutic interventions." (PMID 32660524, 2020). "HMGB1 is abundantly expressed in several leukemia cells, and inhibition of HMGB1 enhances the sensitivity to chemotherapy of leukemia cells." (PMID 31416465, 2019). "Some researchers have found that HMGB1 is overexpressed in many hematological malignancies, such as leukemia and lymphoma, and that it mediates drug resistance through autophagy." (PMID 30157958, 2018). "Studies in leukemia cells have demonstrated that HMGB1 overexpression decreased leukemia cell sensitivity to chemotherapy (i.e., adriamycin, vincristine, cytarabine) and that downregulation of HMGB1 enhanced cell sensitivity to chemotherapy." (PMID 30157958, 2018). "Previous studies have shown that exogenous HMGB1 of levels reach as high as 200 ng/ml during anti-neoplastic immunity of leukemia chemotherapy and induce TNF-α and IL-1β secretion." (PMID 28404891, 2017). "Previous studies have identified the roles of HMGB1 in cancer, with high protein expression in colon, breast, lung, prostate, cervical and gastric cancer, hepatocellular carcinoma and leukemia compared with normal tissues and healthy controls." (PMID 24944700, 2014). "Previous studies have also shown that endogenous HMGB1 regulates autophagy and that HMGB1-induced autophagy promotes resistance to chemotherapy in leukemia cells." (PMID 24944700, 2014). "Similar mechanisms operate in hematological malignancies, where HMGB1 overexpression increases Bcl-2 levels and inhibits caspase-3/9 activation during adriamycin treatment, while HMGB1 knockdown restores chemosensitivity in resistant leukemia cells." (PMID 41465435, 2025). "Additionally, high mobility group box 1 (HMGB1) plays an important role in leukemia pathogenesis and chemotherapy resistance." (PMID 41462004, 2025). "(Hmgb1), a DNA chaperone protein that is overexpressed in tumor cells and can trigger inflammation, cell migration, and tumor metastasis, is also highly expressed in leukemia cells, suggesting a potential role in promoting leukemia progression." (PMID 38730491, 2024). "Interestingly, HMGB1 has been reported to also regulate ferroptosis; in one study with NRAS-mutant leukemia cells, it was shown that HMGB1-deficient cells show decreased ferroptotic cell death." (PMID 37568677, 2023). "HMGB1 also regulates ferroptosis via the Ras-JNK/p38 pathway in leukemia." (PMID 36324584, 2022). "The ROS production was inhibited upon HMGB1 silencing followed by erastin treatment in leukemia." (PMID 36474713, 2022). "Besides, HMGB1 has been found to play a vital role in apoptosis, ferroptosis, and autophagy in leukemia cells." (PMID 36466092, 2022). "It is hypothesized that HMGB1 promotes the secretion of TNF‐α by leukemia cells through the activation of the MAPK signaling pathway and participates in tumor cell immune regulation." (PMID 33140586, 2021). "Apoptosis was halted when employed extracellular HMGB1 into leukemia cells." (PMID 34933679, 2021).
leukemia (continued). "Next, we performed functional analysis to investigate whether HMGB1 participates in AML development by impeding myeloid differentiation through use of the PMA/ATRA-induced differentiation model of THP-1/NB4 leukemia cell lines." (PMID 33128580, 2021). "Combined with the result of Elisa, we assumed that leukemia cells might encounter necroptosis and HMGB1 was released rapidly." (PMID 34933679, 2021). "HMGB1, as a critical anti-apoptotic and pro-autophagic protein, has been reported to be overexpressed and released following chemotherapy and radiation therapy in many cancers including leukemia cells." (PMID 33128580, 2021). "Moreover, treating leukemic cells with chemotherapeutic drugs leads to the translocation of HMGB1, which is involved in autophagy and ultimately promotes chemoresistance in leukemia." (PMID 32660524, 2020). "Moreover, HMGB1-dependent autophagy induces chemotherapy resistance in leukemia and multiple myeloma." (PMID 32660524, 2020). "On the contrary, autophagy induced by exogenous HMGB1 could promote chemotherapeutic resistance in leukemia cells." (PMID 30081847, 2018). "Also, exogenous HMGB1 positively correlated with the clinical status in childhood leukemia and stimulated leukemic cells to secrete TNF-α." (PMID 28404891, 2017). "HMGB1 has been revealed to be constitutively activated in a wide variety of human tumor tissues and cell lines, including colorectal, breast, lung, prostate, cervical, stomach and liver cancer, as well as leukemia." (PMID 25574225, 2015). "It has been demonstrated that leukemia cells sensitivity to chemotherapeutic agents increases by inhibiting HMGB1 release; conversely, leukemia cells resist to cell death by overexpressing HMGB1; finally, pretreatment with exogenous HMGB1 increases leukemia cells drug resistance." (PMID 23509727, 2013). "Nurse-like cells (NLC) represent a population of leukemia-associated macrophages expressing CD14, CD45, HLA-DR, CD33, and CD68, which are induced by CLL cells through nicotinamide phosphoribosyl transferase (NAMPT) and high-mobility group protein B1 (HMGB1) signaling." (PMID 37064123, 2023). "Therefore, we hypothesized that extracellular HMGB1 acts on leukemia cells mainly by interacting with RAGE." (PMID 34933679, 2021). "However, how the released HMGB1 acts on leukemia cells remain elusive." (PMID 34933679, 2021). "Additionally, exogenous HMGB1 directly induces autophagy and cell survival in leukemia cells." (PMID 34445246, 2021). "High mobility group box 1 (HMGB1) is a key regulator of erastin-induced ferroptosis via the RAS-JNK/p38 pathway and is also expected to be a potential drug target in leukemia." (PMID 35111195, 2021). "On the other hand, the arising ROS level can oxidize HMGB1, which makes it more liable to bind to TLR4, and then leads to the deterioration of leukemia cells." (PMID 34933679, 2021). "Doxorubicin-treated leukemia cells induce CRT surface exposure and HMGB1 release in the TME is preserved, although other mediators of immunogenicity in this system remain to be defined." (PMID 34711820, 2021). "HMGB1 also increases the expression of monocyte chemoattractant protein 1 (MCP1) and myeloid cell leukemia 1 (Mcl1) to promote the migration of human leukemia monocytic THP1 cells, which is inhibited by glycyrrhizin (GL)." (PMID 32660524, 2020). "Similar to leukemia (HL-60 & K562) and HBE cells in our previous studies, HMGB1 expression was high in all five thyroid cancer cell lines (K1, KTC-1, TPC-1, FTC-133 & FRO) and yet low in normal human thyroid cells HT-ori3." (PMID 31331356, 2019). "We pretreated leukemia cells with rHMGB1 before treated with ADM and found that extracellular promoted autophagy and protected cells from apoptosis, which suggested that extracellular HMGB1 play an protective role in chemotherapeutic treatments." (PMID 34933679, 2021).
leukemia (continued). "The extracellular and endogenous HMGB1 could also activate autophagy through PI3K-MEK-ERK and PI3K/Akt/mTORC1 pathways and mediate the drug resistance to chemotherapy in leukemia cells." (PMID 33128580, 2021). "High mobility group box 1 (HMGB1) is a non-histone nuclear protein which has been intensively studied in various physiological and pathological processes including leukemia." (PMID 33128580, 2021). "HMGB1 gene transfection can increase the LC3-II level and inhibit the rapamycin complex 1 (mTORC1) pathway to strongly induce autophagy and promote chemoresistance in leukemia cells." (PMID 32660524, 2020). "Similarly, restoration of miR-181b sensitize leukemia cells to doxorubicin (DOX) and cytarabine (ara-C) by downregulating MCL-1 and high mobility group box-1 (HMGB1) expression." (PMID 32164715, 2020). "For example, HMGB1 induces drug resistance by activating leukemia cell autophagy via the PI3K/Akt/mTORC1 pathway, and reduced expression of HMGB1 activates mTOR and promotes the phosphorylation of Akt and p70S6k, inhibiting leukemia cell autophagy and increasing drug sensitivity." (PMID 30157958, 2018). "Viable leukemia cells became strongly positive for HMGB1 predominantly in the cytoplasm after ULMW-HA stimulation, suggesting that HMGB1 is actively translocated from the nucleus to the cytosol after ULMW-HA stimulation and is eventually secreted into the extracellular space." (PMID 28569787, 2017).
glioblastoma (46 papers, 2012 to 2025). The most malignant astrocytic tumor (WHO grade IV). "For instance, miR-142-3p, present in exosomes from M1 macrophages, targets high mobility group box 1 (HMGB1) and influences tumor immune escape in glioblastoma by modulating the PD-1/PD-L1 checkpoint." (PMID 41019058, 2025). "When human glioblastoma cells undergo necrosis, HMGB1 is released into the extracellular environment, where it can act on adjacent cells to promote tumor progression." (PMID 38529373, 2024). "HMGB1 regulates the migration of T98G glioblastoma cells through the RAGE/MEK/ERK signaling pathway." (PMID 38529373, 2024). "Nevertheless, our understanding of the interplay between peripheral inflammation and HMGB1 in the progression and prognosis of glioblastoma is essential and requires further research." (PMID 38003396, 2023). "The concentrations of IL-1β, IL-6, IL-8, IL-10, TNFα, and HMGB1 confirmed that inflammation was a critical component of glioblastoma progression." (PMID 38003396, 2023). "In glioblastoma cells, NETs-derived high mobility group protein 1 (HMGB1) bound to receptor for advanced glycation endproducts (RAGE) and upregulated the NF-κB signaling in tumor cells." (PMID 37958984, 2023). "A grade-dependent enhancement of the TREM1/HMGB1 axis in the glioblastoma microenvironment compared to normal brains was confirmed using clinical tissue samples and western blot technique." (PMID 36249290, 2022). "Similar to that seen in glioblastoma, GC-derived EVs transport high-mobility group box-1 (HMGB1) activates signal transducer and activator of transcription 3 (STAT3) and elevates the expression of PD-L1 in neutrophils, thereby inhibiting T-cell immunity." (PMID 35090497, 2022). "By analyzing the concentration of HMGB1 and of Hsp70 in supernatants of glioblastoma cell cultures treated with fractionated Radiotherapy an increase in these DAMPs was seen (In this studies the ICD inducing capacity of temozolomide was found to be limited)." (PMID 35046546, 2022). "As previously reported for U251MG glioblastoma cells, a 6-day exposure period to HMGB1-fl resulted in a strong inhibition of proliferation of the HeLa, HT-29 and HCT-116 cell lines." (PMID 35887213, 2022). "Under hypoxic conditions, U118 glioblastoma cells were shown to release up to 50-fold higher HMGB1 levels than under normoxic conditions." (PMID 34360919, 2021). "They showed that miR-142 overexpression suppresses cell proliferation and induces apoptosis by targeting high mobility group box protein 1 (HMGB1) via the Wnt/β-catenin signaling pathway in glioblastoma cells." (PMID 35194440, 2021). "Other groups have reported cell death through a previously undescribed mechanism characterized by giant mitochondria formation when recombinant HMGB1 is added to glioblastoma and multiple other human cancer cell lines." (PMID 29543735, 2018). "In this work we studied two danger signals HSP70 and HMGB1 that are expressed and released in response to single or combined treatments of radiation and temozolomide in glioblastoma cells." (PMID 25097859, 2014). "Our results reported a HMGB1 translocation from the nucleus to the cytoplasm and subsequent release into the extracellular space after irradiation in glioblastoma cells." (PMID 25097859, 2014). "Since the immunogenic potential of tumor cells can be determined by their release of danger signals, we analyzed the concentration of HMGB1 and of Hsp70 in supernatants of glioblastoma cell cultures treated with fractionated RT and/or CT." (PMID 24678590, 2014). "High mobility group box 1 (HMGB1) increased the sensitivity of glioblastoma cells to temozolomide." (PMID 35739593, 2022). "It has been found that knockdown of ATG5, ATG7 or ATG12 blocked HMGB1 secretion in diphtheria toxin-treated glioblastoma cells without causing membrane lysis and necrosis, indicating that secretory autophagy is responsible for HMGB1 secretion." (PMID 35927755, 2022).
glioblastoma (continued). "HMGB1 is also a predictor of poor outcomes in glioblastoma patients." (PMID 34360919, 2021). "Our previous work had demonstrated that Nano-DOX could stimulate glioblastoma cells to release DAMPs including HMGB1, adenosine triphosphate (ATP), heat shock protein 90 (HSP90), and calreticulin (CRT)." (PMID 34488792, 2021). "Glycyrrhizin, a direct HMGB1 inhibitor, reportedly could exert inhibitory effects on the proliferation of human glioblastoma U251 cell line." (PMID 33614649, 2021). "In a murine model of glioblastoma, HMGB1 contributes to IL-8 production from tumor cells through HMGB1-RAGE-ERK1/2-NF-κB pathway, which may further attract circulating neutrophils to the tumor site and stimulate them to form NETs." (PMID 34868992, 2021). "Augmented release of HMGB1 by tumor cells on cytotoxic treatment with Ad-TK (+ganciclovir) was even detected to be part of activating effective immune response against glioblastoma cells—a noteworthy fact, as usually the blood-brain barrier prevents immune response." (PMID 26854151, 2015). "In addition, a potential role for HMGB1 has been suggested in promoting growth and migration of human glioblastoma cells." (PMID 23270518, 2012). "Interestingly, galectin-9 (and HMGB1) is elevated in glioblastoma tumor tissue, suggesting that persistent long-term stimulation with galectin-9 may be required for enhanced TIM-3 expression." (PMID 39513882, 2024). "Furthermore, papaverine could cancel the HMGB1-elicited proliferation of human glioblastoma cell lines, both temozolomide (TMZ)-sensitive U87MG and TMZ-resistant T98G cells." (PMID 35408786, 2022). "In addition to analyzing the influence of fractionated RT alone or in combination with TMZ and/or VPA on the cell cycle progression and cell death forms of glioblastoma cells, we were further interested in the release of the danger signals HMGB1 and Hsp70 after the treatments." (PMID 24678590, 2014). "This immunostimulatory environment enhances the chemosensitivity of glioblastoma cells to TMZ, positioning autophagy-mediated HMGB1 release as a favorable, therapy-promoting event." (PMID 41465435, 2025). "In glioblastoma, temozolomide (TMZ) chemotherapy induces a process known as secretory autophagy, which selectively packages and releases HMGB1." (PMID 41465435, 2025). "In irradiated glioblastoma cells, released ATP activates the P2X7 receptor, which in turn promotes both DNA damage repair and the extracellular release of HMGB1." (PMID 41465435, 2025). "HMGB1 and RAGE are overexpressed in glioblastoma, and the impact of RAGE ablation in the tumor microenvironment (TME) on glioblastoma growth appears to be due to reduced tumor inflammation and impaired angiogenesis." (PMID 38529373, 2024). "Functional RNAs, including long non-coding RNAs (lncRNAs) and endogenous non-coding RNAs (microRNAs or miRNAs), have been found to regulate the HMGB1/RAGE axis and affect proliferation in liver cancer and glioblastoma." (PMID 38529373, 2024). "Similar findings were noted in glioblastoma cells, in which NET-derived HMGB1 bound to RAGE and upregulated the NF-κB signaling." (PMID 36050539, 2023). "HMGB1 on NETs was reported to activate RAGE and trigger downstream NF-κB signaling in glioblastoma, while DNA-NETs were found to be responsible for RAGE-dependent activation of pancreatic stellate cells." (PMID 36050539, 2023). "Despite low TLR4 expression glioblastoma stem cells express high levels of TLR2, and its stimulation by high-mobility group box 1 (HMGB1) enhanced the stemness markers of those cells." (PMID 31695691, 2019). "VPA further induced a slightly increased release of HMGB1 in T98G and U251MG glioblastoma cells when combined with fractionated RT." (PMID 24678590, 2014). "Further studies should be carried on to better understand the mechanism of action of HMGB1 and HSP70 on glioblastoma cells and on immune system cells to activate an immune response against tumour." (PMID 25097859, 2014).